CD163 (CD163 molecule)
Diseases named in the same sentence as CD163 in open-access papers (continued):
Sharing a sentence is not in itself a finding about the gene and the disease.
tumor (continued). "Cluster 2 had the highest expression and diversity of M1 and M2 macrophage markers, in particular the general macrophage marker CD68, anti-tumor markers CD169, HLA-DR, STING, and CD38, and pro-tumor markers CD163, CD204, and CD206, and immune checkpoint molecules PD-1 and PD-L1." (PMID 37620318, 2023). "Characterized by the expression of CD68, CD163, and stromal cell-derived factor (SDF)-1, among other markers, NLCs have been equated to tumor-associated macrophages (TAMs) and have been seen to be in close contact with CLL cells in lymphoid tissues of patients." (PMID 38140397, 2023). "Moreover, DCs (including the recently described CD163+ cDC3) are far less numerous than CD163+ macrophages in the tumor microenvironment." (PMID 36459240, 2023). "The expression of CD14 + and CD163 + cells was found to be in between tumor cells." (PMID 37061716, 2023). "Next, we measured the CD68, CD86 (M1 marker) and CD163 protein levels in tumor tissues." (PMID 37875398, 2023). "Therefore, we used immunohistochemistry to evaluate the quantity and distribution of CD4+ lymphocytes, CD8+ lymphocytes, CD68+ macrophages, CD163+ macrophages, and M1-macrophages in the tumor center and invasion front in a cohort of 55 OSCC patients." (PMID 36836239, 2023). "Importantly correlation analyses showed significant co-expression between CMKLR1 and genes specific of tumor associated macrophages (TAM) such as CD14, CD163, MRC1 and HLA-DRA in BC and MPM." (PMID 37539056, 2023). "In vivo studies also demonstrate that the mAb-CD163-PDNPs are highly enriched at the tumor site." (PMID 37111726, 2023). "Regarding the particular cell subtype of TAMs, it has been demonstrated the existence within the tumor of bipotent CD68+ and CD163+ cells capable of differentiating into both osteoclasts and macrophages with different effects on tumor progression and immunodepression." (PMID 36831348, 2023). "In addition, depletion of CD163+ M2-like TAMs in CTCL xenograft mouse models decreased tumor growth, which further supports their critical role in CTCL pathogenesis." (PMID 37427589, 2023). "Spatial analysis of direct cell–cell interaction suggested largely homotypic interactions for tumour cells, endothelial cells and CD163- macrophages; however, tumour cells interacted more with TANs and endothelial cells in higher-grade versus lower-grade histological subtypes." (PMID 37835491, 2023). "Similarly, B cells exhibited a greater tendency to interact with CD163+ macrophages in high-grade tumours, despite the observation that high B cell frequency was indicative of prolonged survival." (PMID 36725934, 2023). "Notably, IDHmt specimens exhibited significantly enhanced CD86+ GAMs, while IDHwt samples showed markedly increased CD163+ GAMs, indicative of M1‐ and M2‐like phenotypes, respectively, in these two distinct subtypes of tumor entities." (PMID 37166058, 2023). "Additionally, we confirmed that CD163 + M2 macrophages were less infiltrated in post-infusion tumor specimens, highlighting that GD2-specific 4SCAR-T cells remodel M2 macrophage-mediated suppressive immune microenvironment." (PMID 36617554, 2023). "Interestingly, CD163 mRNA levels were significantly higher in tumors from patients with residual tumor mass after surgery." (PMID 37876933, 2023). "HNSCC, and particularly OSCC, are known to have a strong immune-suppressive environment, which could explain the low levels of CD163+ cells in the tumor center observed in our cohort." (PMID 36836239, 2023). "Furthermore, we also found a significant relationship between the density of TILs within the tumor nests and stroma, with the density of CD68+ and CD163+ macrophages infiltrating the tumor, and also with the tumor-infiltrating CD8+ T cells." (PMID 37893049, 2023). "In addition, T stage, N stage, TNM stage, adjuvant chemotherapy, CD163 cell infiltration, IL-6 expression, and tumor SUV were significant prognostic factors for RFS (p < 0.05)." (PMID 36983926, 2023).
tumor (continued). "Interestingly, anti-PD-L1+ NP3 treatment decreased the CD163 expression of M2-TAMs and significantly increase the expression of anti-tumour M1 macrophages and cytotoxic CD8 lymphocytes." (PMID 36857852, 2023). "CD163+ TAMs are mostly distributed around the microvasculature of the tumour stroma." (PMID 36928373, 2023). "Besides, significantly positive correlation between APOC1+APOE+ macrophages and CD163+ macrophages were analyzed in tumor nest." (PMID 36709495, 2023). "Interestingly, the trend of CD163 + macrophages was consistent in both the central and marginal regions of the tumor." (PMID 38124204, 2023). "High CD47 tumor cell expression or high counts of CD68 macrophages were significantly associated with elevated levels of all TIL subsets (p < 0.02), CD163 macrophages (p < 0.001), blood vessel invasion (CD31 positive) (p < 0.01), and high tumor cell Ki67 (p < 0.004)." (PMID 36598153, 2023). "However, luminal A tumors were accompanied by low levels of CD163+ TAMs in both tumor nest and tumor stroma." (PMID 36794651, 2023). "Furthermore, RFA alone reduced CD163+ M2 macrophages in distant tumor compared to either RFA-lip-GM-CSF or sham arms (p<0.05, for all comparisons)." (PMID 37883367, 2023). "Notably, tumor-infiltrated CD14+ cDCs express high levels of markers that are characteristic of tumor-associated macrophages (TAMs), such as CD206, MerTK and CD163, suggesting that these cells exhibit TAM-like protumoral functions." (PMID 36949244, 2023). "Furthermore, we performed immunostaining for CD163, a human macrophage marker, and for CD8α, a cytotoxic T cells marker, and the number of intra-tumor positive cells was analyzed." (PMID 36809261, 2023). "Moreover, CCL22 produced by CD163+ TAMs binds to CCR4 on tumor cells which induces EMT and promotes HCC invasiveness in patients." (PMID 36845555, 2023). "Besides tumour cells themselves, TAMs are affected by the tumour stroma, where both CD163 and LILRB1 are present." (PMID 36900335, 2023). "CD68-positive or CD163-positive macrophages were mainly detected in the tumor stroma." (PMID 37749297, 2023). "Moreover, MCs were located within range for direct or paracrine interactions with CD8+ T cells, as well as CD163+ macrophages and tumor cells." (PMID 37190096, 2023). "Furthermore, a correlation with vascular (n=146, p=0.035) and lymphovascular invasion (n=195, p=0.004) and high CD163 mRNA levels was found, both features indicative of an aggressive and invasive tumor phenotype." (PMID 37876933, 2023). "Then, to investigate whether macrophages were recruited in TME by A549S25E cells showing high expression of VEGFA and IL1A, mouse tumor tissues were stained with specific macrophage antibodies for TAM marker CD163 and pan-macrophage marker CD68." (PMID 37968723, 2023). "Additionally, more M2-like macrophages (CD163+) accumulated into the tumor from mice with C. albicans infection and reduced after IL-17A neutralization." (PMID 37067414, 2023). "In addition, CD20+ B cells, CD11c+ dendritic cells and CD163+ macrophages were distributed along the tumor margin but excluded from the tumor core." (PMID 37488287, 2023). "Nonetheless, MHCII + CD163− TAMs accumulate within the regressing lesions (R3, R4) and could also promote the activation of tumor-specific T cells." (PMID 37526660, 2023). "Interestingly, it appears that CD163+ TAMs secrete immunosuppressive cytokines and support tumor progression, invasion, angiogenesis, and metastases." (PMID 36139575, 2022). "We observed dense aggregates of CD163 immunostained macrophages intermixed with tumor cells." (PMID 35885058, 2022). "The results of IHC analyses revealed that the tumor tissues derived from the “Panc 02 + rHSP90α-treated RAW264.7” grafts contained more CD163+ cells but significantly reduced levels of CD4+ T-cells when compared with the tumor masses taken from other groups of mice." (PMID 35053345, 2022).
tumor (continued). "GNB4 expression was notably related to the tumor-associated macrophage (TAM) markers CCL2 (Cor = 0.527, P = 1.64e−28), IL10 (Cor = 0.61, P = 5.02e−40), M2 macrophage marker CD163 (Cor = 0.66, P = 1.01e−48), VSIG4 (Cor = 0.64, P = 5.17e−45), and MS4A4A (Cor = 0.723, P = 1.26e−62)." (PMID 35756485, 2022). "Because tumor-associated MΦ are suggested to be involved in tumor progression and/or aggressiveness, we investigated the distribution and density of CD68 (M1, pro-inflammatory) MΦ and CD163 (M2, anti-inflammatory) MΦ." (PMID 36230513, 2022). "There is alsoevidence in the litera ture that increased CD163 expression is characteristicof PD-L1+ cancer compared to PD-L1.Our results demonstrate that the CD163+ cell content in tumor stroma positivelycorrelates with PD-L1 expression in stromal but not in tumor cells in GC." (PMID 36694901, 2022). "In addition to CD86 protein expression and co‐expression of CD68 and CD163 status, statistically remarkable clinicopathological features that were associated with RFS were TNM stage (P =.001) and tumour differentiation (P =.010)." (PMID 34964155, 2022). "In addition to CD8+ T cells, we also characterized CD4+ T cells, CD20+ B cells, and CD163+ histocytes infiltrating the tumour-related stroma." (PMID 36280845, 2022). "However, TAMs co-express CD163/206 at a higher level than M1- and M2-like macrophages, highlighting that TAMs differ from M2 due to the presence of the tumor." (PMID 36358879, 2022). "To further establish the phenotype of the tumour-associated macrophages (TAMs) that express PDLIM2, we analyzed the percentage of PDLIM2-positive or -negative tumours that expressed low or medium/high levels of CD163." (PMID 36531051, 2022). "It was demonstrated that macrophages could form dense or cohesive aggregates of CD163 cells among the tumor cells, which we called the “immune barrier”." (PMID 35885058, 2022). "We also assessed the tumor-infiltrating macrophages (CD163+CD68+) in tumor samples." (PMID 35836810, 2022). "Moreover, our results indicate that the average number of communicating CD163+ TAMs is a potentially more informative metric than the traditional density of CD163+ TAMs within a sampled area of the tumor." (PMID 35053472, 2022). "Association of PU.1, CD163, and CD20 content with clinical andmorphological characteristics of GC At the next stage, we analyzed theassociation of the PU.1+, CD20+, and CD163+ cell content in the tumor stromawith the clinical and morphological characteristics of the disease." (PMID 36694901, 2022). "Our imaging suggested similar interactions may be occurring in human non-tumor-associated dura as we observed co-localization of CD4+ T cells and HLA-DRA+ cells in addition to CD8+ T cells and CD163+ macrophages near CD31+ stained vasculature." (PMID 35534852, 2022). "In each tumor, a CD163-dominant pattern of infiltration was evident." (PMID 35885058, 2022). "Furthermore, after CD163 + TAMs were sorted from tumour tissues from subcutaneous mice, we observed that the expression of KLF12 and c-myc was significantly decreased in the LncRNA-PACERR knockdown group." (PMID 35526050, 2022). "As CD68+ and CD163+ macrophages are usually detected in cHL tissues and their density within tumor samples has been proposed as being a predictor of poor prognosis, it may be associated with CD14+ CD163+ monocytes as precursors." (PMID 35267668, 2022). "Moreover, CD163+ cells accounted for a larger proportion in tumor samples than normal lung tissues, which was mainly consistent with our initial results of cell typing for macrophages by scRNA-seq." (PMID 36249427, 2022). "CD163 is a marker of M2 macrophages and plays the role of regulating tumor infiltration." (PMID 35515103, 2022).
tumor (continued). "Surgically resected UPS samples were stained by immunohistochemistry (IHC) for the following: tumor-associated immune cells (CD3, CD8, CD163, CD20), immune checkpoints (stimulatory: OX40, ICOS; inhibitory: PD-L1, LAG3, IDO1, PD1), and the adenosine pathway (CD73, CD39)." (PMID 36313661, 2022). "CD163 is a marker of anti-inflammatory M2 macrophages supporting tumor growth." (PMID 35159079, 2022). "As a result of examining the expressions of six types of macrophage markers (pan-macrophage [CD68, F4/80], M1-type [CD80, CD86], and M2-type [CD163, CD206] macrophage markers), it was revealed that only the expression of the tumor-promotive M2-type marker CD163 was significantly reduced." (PMID 36497144, 2022). "Second, we could have identified a more restricted population of CD68+CD163+CD206+ M2 TAMs in a tumor microenvironment that is relatively less infiltrated by other CD68+CD163+ TAMs." (PMID 36230752, 2022). "Although CD163+ cells were observed in perivascular space and in inflammatory areas of potential glial polarization, we focused our quantification on the tumor core." (PMID 35805021, 2022). "Our data also show that patients with high densities of suppressor FoxP3+ or CD163+ cells in their tumor center or the invasive margin, albeit with high numbers of CD8+ cells, had trends for shorter OS compared to those who displayed low FoxP3+ or CD163+ cell frequencies." (PMID 36551693, 2022). "Taken together, these results indicate an immunomodulatory function of norepinephrine release by sympathetic nerve terminals that would contribute to limit the proportion of pro-tumorigenic and immunosuppressive CD163+ macrophages in pancreatic preneoplastic and tumor tissues." (PMID 35418199, 2022). "Furthermore, patients with high CD163 expression showed a remarkably greater presence of larger tumour diameter and poorer differentiation (P =.04)." (PMID 34964155, 2022). "Besides, CD68 and CD163 were more co‐expressed in tumor tissues with high PTX3 expression than in tumor tissues with low PTX3 expression." (PMID 35855654, 2022). "A second hypothesis would be that a greater Treg/CD163 expression may be due to the expression of chemotactic cytokines or chemokines, or both, to attract these cells into the tumor, thus shaping a more favorable cancer microenvironment." (PMID 36551693, 2022). "At the same, a significant number of M2 macrophages (CD163+ cells) were found in the tumor microenvironment, which could have an unfavourable adverse effect on the course of the neoplastic process." (PMID 34636027, 2022). "We analyzed the expression of CCR2, a key chemotactic receptor on monocytes responsible for their recruitment into tumor mass, and CD163, a clearance receptor for hemoglobin-haptoglobin complex, which expression on TAMs correlates with tumor growth and metastasis in various cancers including CRC." (PMID 36733385, 2022). "However, when densities of FoxP3+ and CD163+ cells were jointly considered, either in the tumor center or the invasive margin, the statistical difference was improved." (PMID 36551693, 2022). "CD68+ and CD163+ macrophage cells could be detected in tumor stroma, connective tissues, and around vessels." (PMID 35877331, 2022). "Additional correlation analyses showed that IL7R expression was significantly associated with markers of cells involved in immunosuppression such as CD68, CD163, MRC1, and IL10 (tumor‐associated macrophages), CD4, FOXP3 (regulator T lymphocytes) and CD274 (PD‐L1)." (PMID 36054746, 2022). "Moreover, the expression of CD163 in primary tumor tissue was significantly higher than that in adjacent normal tissue at both the mRNA and protein levels in RCC patients based on the TCGA and Clinical Proteomic Tumor Analysis Consortium (CPTAC) databases." (PMID 35443741, 2022).
tumor (continued). "However, more extensive tumor sampling from whole-tissue sections is expected to provide more accurate data and potentially strengthen the results based on spatial CD163+ TAM metrics from limited TMA cores." (PMID 35053472, 2022). "The CD163 expression data were divided into four groups: tumor tissue with high or low cellular expression, normal tissue with different cellular expression, tumor tissue with high/low expression in the stroma, and normal tissue with different stroma expressions." (PMID 36551651, 2022). "At the same time, myeloid CD163+ cells infiltrating the tumor are the predominant cells and may contribute to tumor escape from the immune response." (PMID 36297616, 2022). "Therefore, CD163 has great potential to be used as a biomarker to evaluate early inflammatory response, tumor recurrence, and patient survival, among others." (PMID 36551651, 2022). "High number of CD163+ cells was found in peritumoral region of tumor and in liver metastases." (PMID 36686729, 2022). "In this model, the number of infiltrating F4/80+, CD11b+ and CD68+ macrophages increased drastically 8 weeks after injection of tumor cells into the peritoneal cavity, and macrophages displayed M2-polarization markers (by the expression of CD163, CD206 and CX3CR1)." (PMID 35682890, 2022). "V(Hb)@DOX could effectively limit the recruitment of CD163+ M2-type macrophages and improve tumor hypoxia by reducing HIF-1α expression." (PMID 36311793, 2022). "Therefore, it is possible that the reduction in CD163 by Nanog+F10-EVs reduced the suppressive effect on T cells, resulting in increased anti-tumor immunity activity." (PMID 36497144, 2022). "TNFAIP8 correlated positively with high M2-like CD163-positive tumor-associated macrophages (TAMs) and non-GCB cell of origin phenotype." (PMID 36358737, 2022). "In addition, M1 macrophages are anti-tumor surface, which plays a role in inhibiting tumor progress, while M2-activated macrophages promote tumor progress by secreting CD163 and other vascular generating factors." (PMID 36685506, 2022). "Tumor-mediated activation of STAT3 in CD163+ TAMs resulted in pro-tumor TAM polarization." (PMID 36686729, 2022). "In particular, the presence of CD163+ cells outside the GBM tumor tissue were very low." (PMID 36611806, 2022). "Similarly, all NND-based metrics and the average number of adjacent CD163+ TAMs can be used in tumor images of any size and can also be computed for other immune cell populations and can be applied to other solid tumor types." (PMID 35053472, 2022). "In contrast, BCL2 and CD163 had low expressions in the tumor groups in all databases." (PMID 36551651, 2022). "Multiplex IF-IHC of Rab37, CHI3L1 and CD163 was performed on 23 tumor specimens." (PMID 34987649, 2022). "Subgroup A has a high expression of pro-tumor markers (CD163, PCOLCE2, IL-6) related to immune suppression and ECM remodeling while subgroup B has a low expression of pro-tumorigenic and immunosuppressive markers with an upregulation of genes linked to interferon signaling." (PMID 36035994, 2022). "We could demonstrate a direct correlation between the frequencies of CD8+ cells with CD163+ and/or FoxP3+ cells in single or combined tumor compartments (IM and/or TC) in the vast majority of patients’ tumors." (PMID 36551693, 2022). "However, it is also known that CD163 expression is induced by pro-inflammatory cytokines such as IL-6, glycolytic metabolites produced by proliferating tumor cells such as lactate, and hormones including glucocorticoids." (PMID 35269507, 2022). "The tumor infiltrating Rab37+CHI3L1+ cells were highly enriched with CD163+ M2 TAMs in the tumor sections from patients with advanced tumor stages, whereas early staged tumors displayed a low abundance of infiltrating Rab37+CHI3L1+CD163+ M2 TAMs and scattered intratumoral CHI3L1." (PMID 34987649, 2022).